STARD13 (StAR related lipid transfer domain containing 13)
Diseases named in the same sentence as STARD13 in open-access papers (continued):
Sharing a sentence is not in itself a finding about the gene and the disease.
breast cancer (continued). "Similar to HOXD-AS1, the STARD13 (DLC2, a RhoGAP) 3’UTR acts as a ceRNA and increases Bcl-2 modifying factor (BMF) expression by competitively binding with miR-125b in breast cancer." (PMID 34663417, 2021). "By analyzing the mRNA microarrays from TCGA, we determined that LATS1/2 level was positively correlated with STARD13, CDH5, HOXD1, and HOXD10 levels in breast cancer tissues, respectively." (PMID 29848346, 2018). "Consistently, ectopic expression of STARD13-correlated ceRNAs-3′UTRs in breast cancer cells elevated LATS1/2 levels, while the knockdown of STARD13-correlated ceRNAs decreased LATS1/2 levels." (PMID 29848346, 2018). "The CCR2 3′UTR acted as a ceRNA for STARD13 and helped to inhibit cell metastasis by repressing EMT in breast cancer." (PMID 30545369, 2018). "A STARD13-correlated ceRNA network inhibited EMT and metastasis of breast cancer in vitro and in vivo." (PMID 30545369, 2018). "Despite multiple relationships, our study provide solid evidences to outline the novel roles of STARD13-, CDH5-, HOXD1-, and HOXD10-3’UTRs in modulating breast cancer metastasis via competing for miR-9, miR-10b and miR-125b in vitro and in vivo." (PMID 26985770, 2016). "Another research showed that STARD13 3′UTR could play as a ceRNA for BMF to enhance apoptosis and be used as a potential therapeutic target in breast cancer cells." (PMID 37794108, 2023). "The miR-125b/STARD13 regulatory axis has been confirmed in our previous studies, and we indicate that STARD13 3’UTR suppresses breast cancer stemness by inhibiting YAP/TAZ activity through co-regulating Hippo and RhoA (Ras homolog gene family, member A) signaling." (PMID 35057866, 2022). "Previous studies in breast cancer lines have shown that knockdown of StarD13 did not affect the migratory behavior of cells and the regulatory effect was performed by DCL-1." (PMID 30899277, 2019). "This promotes us to explore the functions of STARD13-, CDH5-, HOXD1-, and HOXD10-3’UTRs in breast cancer metastasis and whether they possess the functions through acting as ceRNAs." (PMID 26985770, 2016). "In sum, these data testify our hypothesis that STARD13, CDH5, HOXD1, and HOXD10 may bind with miR-9, miR-10b and miR-125b to suppress breast cancer metastasis." (PMID 26985770, 2016). "Notably, 3’UTRs of these genes suppress breast cancer metastasis via inhibiting epithelial-mesenchymal transition (EMT) in vitro and in vivo, which are activated through the crosstalk between STARD13 and its ceRNAs in 3’UTR- and miRNA-dependent manners." (PMID 26985770, 2016). "As miR-9, miR-10b, and miR-125b are confirmed to promoting breast cancer metastasis via enhancing EMT, we further tested whether STARD13- and its ceRNAs-3’UTRs exerted the metastasis-inhibitory effects through suppressing EMT." (PMID 26985770, 2016). "Looking at its level of expression by IHC we revealed that StarD13 is highly expressed in non-tumor in situ form of breast cancer and it is downregulated in grades I and II, suggesting the potential role of StarD13 as a tumor suppressor in breast cancer." (PMID 24627003, 2014). "To summarize, STARD13, which is triggered by CDH5, HOXD1, and HOXD10 ceRNAs, stimulates Hippo signaling by acting as a ceRNA for upregulating the LATS1/2 and blocks the Rho GTPase/F-actin pathway, inhibiting YAP/TAZ and suppressing EMT and CSC development in breast cancer." (PMID 39170516, 2024). "Our recent work has confirmed that STARD13, CDH5, HOXD1, and HOXD10 could co-regulate each other through competing for several shared miRNA binding sites, and thus formed a ceRNA network to coordinately inhibit breast cancer EMT and metastasis, which is denoted as STARD13-correlated ceRNA network." (PMID 29848346, 2018). "To investigate whether STARD13-correlated ceRNA network is involved in breast CSC formation, we first detected the expression levels of STARD13, CDH5, HOXD1, and HOXD10 in a pool of CSCs naturally arising within breast cancer cells." (PMID 29848346, 2018).
hepatocellular carcinoma (15 papers, 2009 to 2024). A malignant tumor that arises from hepatocytes. "Overexpression of StarD13 was found to associate with significant decrease in cell growth and proliferation in hepatocellular carcinoma." (PMID 24627003, 2014). "Immunohistochemistry and data microarray analysis revealed a lower expression of StarD13 in ovarian cancer tissues as compared to the normal ovarian tissues, which is similar to the results observed in lung and hepatocellular cancers." (PMID 34958986, 2022). "STARD13 has been reported to exert anti-tumor roles in various cancers which include prostate cancer and hepatocellular carcinoma." (PMID 34281560, 2021). "Researchers have shown that StarD13 is underexpressed in hepatocellular carcinoma and that the overexpression of StarD13 significantly decreases cell growth and proliferation." (PMID 32900380, 2020). "Consistent with its role as a tumor suppressor, StarD13 also decreased cell motility in hepatocellular carcinoma, and localized to focal adhesions in HeLa cells." (PMID 32900380, 2020). "STARD13/DLC2 encodes a Rho GTPase activating protein and was identified from a region of chromosome 13 exhibiting a loss of heterozygosity in hepatocellular carcinoma." (PMID 21226949, 2011). "A recent study indicated that STARD13 could enhance 5-FU sensitivity by suppressing cancer stemness in hepatocellular carcinoma cells via attenuating YAP transcriptional activity." (PMID 36241975, 2022). "Therefore, we propose that the circ_0003570/miR‐182‐5p/STARD13 axis may play an important role in hepatocellular carcinoma progression." (PMID 36241975, 2022). "On the other hand, we found that STARD13 could inhibit proliferation and metastasis of hepatocellular carcinoma.These results showed that circ_0003570 functions as an endogenous “sponge” by competitively binding miR-182-5p and thus abolishing miRNA-mediated repression of STARD13." (PMID 36241975, 2022). "STAR-related lipid transfer domain containing 13 (StarD13), also known as deleted in liver cancer 2 protein (DLC-2), may be involved in the regulation of cell proliferation and apoptosis, acting as a tumor suppressor in hepatocellular carcinoma." (PMID 30899277, 2019).
prostate carcinoma (7 papers, 2009 to 2022). A carcinoma that arises from epithelial cells of the prostate gland. "For instance, miR-9-5p suppresses prostate cancer progress by targeting StarD13, and miR-9 downregulates CDX2 expression in gastric cancer cells." (PMID 32121275, 2020). "This study aims to investigate the effects of inhibiting microRNA-9-5p (miR-9-5p) on the expression of StAR-related lipid transfer domain containing 13 (StarD13) and the progress of prostate cancer." (PMID 30899277, 2019). "StarD13 was predicted to be a direct target of miR-9-5p in prostate cancer in our bioinformatics analysis." (PMID 30899277, 2019). "The mRNA expression levels of miR-9-5p and StarD13 were determined in several prostate cancer cell lines." (PMID 30899277, 2019). "Our results show that miR-9-5p was highly expressed and StarD13 was suppressed in prostate cancer cells." (PMID 30899277, 2019). "Our results show that miR-9-5p plays a powerful role in the growth, invasion, migration and epithelial–mesenchymal transition (EMT) of prostate cancer cells by regulating StarD13." (PMID 30899277, 2019). "We aimed to show whether miR-9-5p and StarD13 might act as a novel therapeutic target for the treatment of prostate cancer." (PMID 30899277, 2019). "StarD13 expression in prostate cancer cells was notably lower, particularly in DU145 cells." (PMID 30899277, 2019).
colorectal cancer (5 papers, 2019 to 2024). A primary or metastatic malignant neoplasm that affects the colon or rectum. "In contrast with its tumor suppressor function however, we have demonstrated that StarD13 positively regulates cell migration of different cancer types including astrocytoma, breast, lung, and colorectal cancer." (PMID 34958986, 2022). "The StarD13 gene as a target of miR-720 could regulate the abilities of cell growth, migration and invasion in colorectal cancer." (PMID 30899277, 2019).
liver cancer (5 papers, 2011 to 2022). An epithelial or non-epithelial malignant neoplasm that arises from the liver. "STARD13 is a Rho GTPase signaling protein and a tumor suppressor in liver cancer." (PMID 35579274, 2022). "In addition, we investigated the mechanisms of pro-metastasis for miR-125b and found that STARD13, (StAR-related lipid transfer domain containing 13) also known as DLC2 (deleted in liver cancer cells) with a Rho-GAPase-activating protein (RhoGAP), was a target protein of miR-125b." (PMID 22693547, 2012).
astrocytoma (4 papers, 2014 to 2022). "In a previous study from our laboratory, we observed an increase in ERK phosphorylation in response to STARD13 knockdown in astrocytoma cells, also placing ERK downstream from CDC42." (PMID 30781697, 2019). "This was in accordance with a previous study in astrocytoma where StarD13 was shown to be overexpressed in grades III and IV as compared to grades I and II of the tumor." (PMID 24627003, 2014). "Also, previous data in astrocytoma suggest a potential role of StarD13 as a tumor suppressor." (PMID 24627003, 2014).
lung carcinoma (4 papers, 2020 to 2022). "In a recent study, we showed that StarD13 depletion increases invadopodia formation through Cdc42 in normal lung cells and in lung cancer cells." (PMID 34958986, 2022). "Consistently, western blot analysis revealed a significant underexpression (higher than 4 fold) of StarD13 in A549 lung cancer cells compared to the normal lung cells WI38." (PMID 32900380, 2020). "In summary, this study defined distinct roles of StarD13 in lung cancer cell migration and invasion through its differential regulation of Rho GTPases." (PMID 32900380, 2020). "We knocked down StarD13 expression in A549 lung cancer cells and tested the effect on cell migration and invadopodia formation using time lapse imaging and invasion assays." (PMID 32900380, 2020). "In conclusion, StarD13 plays distinct roles in lung cancer cell migration and invasion through its differential regulation of Rho GTPases." (PMID 32900380, 2020). "This study established StarD13 as a potential tumor suppressor in lung cancer, similarly to other solid tumors." (PMID 32900380, 2020). "This was also supported by this study that demonstrates that StarD13 positively contributes to the migration of lung cancer cells." (PMID 32900380, 2020). "To investigate the tumor suppressor function of StarD13 in lung cancer, we examined its expression levels in lung cancer and normal lung biopsy tissue sections obtained from patients with Stage II Non-small cell lung adenocarcinoma." (PMID 32900380, 2020). "Data obtained from analyzing the expression levels of StarD13 in patient tissues compared to normal tissues revealed an underexpression of StarD13 in lung cancer, as has been described for other tumor types." (PMID 32900380, 2020). "Conversely, StarD13 was required for lung cancer cell migration." (PMID 32900380, 2020). "Invadopodia signaling has not yet been studied in lung cancer and StarD13 is a key regulator of RhoGTPases, hence of invadopodia." (PMID 32900380, 2020). "In addition, the depletion of StarD13 increased cell proliferation and viability in WI38 and A549 cells, suggesting that StarD13 might potentially be a tumor suppressor in lung cancer." (PMID 32900380, 2020). "The data showed that unlike 2D migration, StarD13 inhibits lung cancer cell invasion." (PMID 32900380, 2020).
gastric cancer (3 papers, 2019 to 2020). A primary or metastatic malignant neoplasm involving the stomach. "This was reported in another study which further identified StarD13 as a miR-125b microRNA target and showed that StarD13 silencing (being complementary to StarD13’s 3’UTR) increases the metastatic ability of gastric cancer." (PMID 32900380, 2020). "For instance, miRNA-125b promotes the invasion and metastasis of gastric cancer cells by targeting StarD13 and NEU1." (PMID 30899277, 2019). "StarD13 is a well-documented direct and functional target of miR-125b in gastric cancer, with its upregulation inhibiting invasion and metastasis." (PMID 30899277, 2019).
glioblastoma (3 papers, 2019 to 2021). The most malignant astrocytic tumor (WHO grade IV). "Furthermore, a Genome-Wide Analysis integrating a paired copy number and gene expression survey on glioblastoma samples concluded that StarD13 is a potential tumor suppressor gene that could be involved in the resistance of this tumor type to etoposide." (PMID 32900380, 2020). "StarD13 (START-GAP2) is a GTPase-activating protein (GAP) that specifically inhibits RhoA and Cdc42 in glioblastoma cells and other tumor models." (PMID 31698752, 2019). "Moreover, STARD13, a GTPase-activating protein (GAP), inhibits RhoA and Cdc42 specifically in glioblastoma cells and other types of tumor models." (PMID 34952924, 2021).
pancreatic cancer (3 papers, 2021 to 2024). "Meanwhile, miR-125b-5p targeting the tumor suppressor STARD13 exhibited a pro-metastatic role in the exosomes secreted by pancreatic cancer." (PMID 38362150, 2024). "This is in consistence with the literature about the oncogenic function of miR-877-3p in Pancreatic Cancer by interacting with STARD13." (PMID 35600882, 2022).
Alzheimer disease (2 papers, 2016 to 2026). A progressive, neurodegenerative disease characterized by loss of function and death of nerve cells in several areas of the brain leading to loss of cognitive function such as memory and language. "The STARD13 gene has moreover been associated (P ≤ 1 × 10−5) with plasma levels of amyloid beta peptides that, among other things, play a role in Alzheimer's disease and hypertension." (PMID 26446717, 2016). "Subcluster 2 expressed high levels of white matter associated genes (NRP1, MERTK, and NCKAP5) while subcluster 3 displayed a disease‐associated signature (STARD13, MITF, GPNMB, and DPYD) previously observed in Alzheimer's disease (AD) and Multiple Sclerosis (MS)." (PMID 41283828, 2026).
liver fibrosis (2 papers, 2018 to 2024). "For example, pretreating M1 macrophages with phillygenin downregulates their secretion of miR-125b-5p, reversing the activation of HSCs and attenuating liver fibrosis by targeting StAR-related lipid transfer domain-containing 13 (Stard13)." (PMID 39396032, 2024). "In summary, our findings uncover a miR-125b-Stard13-RhoA-α-SMA signaling cascade in HSCs and highlight its importance in hepatic fibrosis." (PMID 30195793, 2018). "In this study, we disclosed a miR-125b-Stard13-RhoA-α-SMA signaling pathway in HSCs and revealed a promotive role of miR-125b in HSC activation and liver fibrosis." (PMID 30195793, 2018). "Therefore, our findings identify a miR-125b-Stard13-RhoA-α-SMA signaling cascade in HSCs and highlight its importance in hepatic fibrosis." (PMID 30195793, 2018).
lung adenocarcinoma (2 papers, 2020 to 2021). A carcinoma that arises from the lung and is characterized by the presence of malignant glandular epithelial cells. "Collectively this data confirms that StarD13 is a tumor suppressor in lung adenocarcinoma and uncovers a RhoA-dependent mechanism for regulating cell migration and adhesion." (PMID 32900380, 2020). "StarD13 also showed a lower expression in the lung adenocarcinoma cell line A549 compared to normal lung cells, WI38." (PMID 32900380, 2020). "In line with its role in other solid tumors, the increase in cell viability and cell division in vitro upon silencing of StarD13 in lung normal and cancer cells further suggesting the potential tumor suppressor role of StarD13 in lung adenocarcinoma." (PMID 32900380, 2020). "Therefore we sought to elucidate the mechanism through which the StarD13/RhoA/Rac1 pathway regulates cell migration in lung adenocarcinoma cells, by examining its effects on cell adhesion dynamics." (PMID 32900380, 2020). "This study characterizes the role of StarD13 in lung adenocarcinoma cells survival." (PMID 32900380, 2020). "Finally, and for the first time, we demonstrate a role for StarD13 in invadopodia formation, matrix degradation and invasion of lung adenocarcinoma cells by regulating Cdc42." (PMID 32900380, 2020). "Hence, this suggested that the inhibition of lung adenocarcinoma cell motility in StarD13-depleted cells could be through the indirect inhibition of Rac1, caused by the constitutive activation of RhoA." (PMID 32900380, 2020).
osteosarcoma (2 papers, 2020 to 2022). A usually aggressive malignant bone-forming mesenchymal neoplasm, predominantly affecting adolescents and young adults. "PUM2 represses osteosarcoma by competitively binding to the STARD13 3'UTR against miR-590-3p and miR-9." (PMID 34998399, 2022).